SERINC5 (serine incorporator 5)
Description:
Restriction factor required to restrict infectivity of lentiviruses, such as HIV-1: acts by inhibiting an early step of viral infection. Impairs the penetration of the viral particle into the cytoplasm. Non-ATP-dependent, non-specific lipid transporter for phosphatidylserine, phosphatidylcholine, and phosphatidylethanolamine. Functions as a scramblase that flips lipids in both directions across the membrane. Phospholipid scrambling results in HIV-1 surface exposure of phosphatidylserine and loss of membrane asymmetry, which leads to changes in HIV-1 Env conformation and loss of infectivity. Enhances the incorporation of serine into phosphatidylserine and sphingolipids. May play a role in providing serine molecules for the formation of myelin glycosphingolipids in oligodendrocytes (By similarity).
Synonyms: C5orf12; TPO1
Tractability: Antibody: UniProt places it where antibodies can reach, with high confidence; its Gene Ontology location is reachable by antibodies, with high confidence; UniProt predicts a signal peptide or a membrane-spanning region; the Human Protein Atlas places it where antibodies can reach. PROTAC: ubiquitination databases record sites on it.
Safety:
Unwanted effects reported when the protein is acted on. In parentheses: how it was acted on, where the effect was seen, and who reports it.
adverse events (source: ClinPGx)
Gene: Protein-coding gene on chromosome 5 (80,111,228 to 80,256,048, reverse strand). Ensembl gene ENSG00000164300.
Subcellular location: Cell membrane; Cytoplasm, perinuclear region
Subcellular location (Human Protein Atlas): Cytosol; Plasma membrane; Centrosome; Vesicles
Pathways (Reactome):
Metabolism: Serine metabolism
Gene Ontology:
Molecular function: molecular carrier activity; phospholipid scramblase activity
Biological process: antiviral innate immune response; plasma membrane phospholipid scrambling; phosphatidylserine metabolic process
Cellular component: cytosol; extracellular exosome; plasma membrane; membrane; Golgi apparatus; myelin sheath; perinuclear region of cytoplasm
Genetic constraint (gnomAD): Loss-of-function variants: 30 observed, 44.69 expected, observed/expected ratio (o/e) 0.67, 90% interval 0.5 to 0.91. The upper end of that interval is the gene's LOEUF score, 0.91, which puts it in group 3 of 6, group 1 being the genes least tolerant of losing a copy. Missense variants: 470 observed, 511.21 expected, observed/expected ratio (o/e) 0.92, 90% interval 0.85 to 0.99. Synonymous variants: 200 observed, 193.62 expected, observed/expected ratio (o/e) 1.03, 90% interval 0.92 to 1.16.
Homologues: Orthologues: chimpanzee SERINC5 (99% identical), macaque SERINC5 (92% identical), pig SERINC5 (90% identical), dog SERINC5 (90% identical), rabbit SERINC5 (87% identical), guinea pig SERINC5 (83% identical), mouse Serinc5 (82% identical), rat Serinc5 (80% identical), tropical clawed frog serinc5 (71% identical), zebrafish serinc5 (61% identical), Caenorhabditis elegans R11H6.2 (36% identical), Caenorhabditis elegans Y57E12AL.1 (34% identical), and 1 more. Paralogues in human: SERINC4 (41% identical), SERINC3 (39% identical), SERINC2 (38% identical), SERINC1 (37% identical).
Diseases named in the same sentence as SERINC5 in open-access papers:
SERINC5 is named in the same sentence as 12 diseases in open-access papers, as found by Europe PMC text mining. Sharing a sentence is not in itself a finding about the gene and the disease. The quoted sentences say what the papers report.
HIV-1 infection (11 papers, 2018 to 2025). The type species of lentivirus and the etiologic agent of acquired immunodeficiency syndrome (AIDS). "Our study reveals an important role of K130 polyubiquitination and K33/K48-linked ubiquitin chains in HIV-1 infection by regulating SERINC5 post-Golgi trafficking and degradation." (PMID 35474067, 2022). "Collectively, these findings demonstrate that Nef’s essential function during HIV-1 infection is to counteract the antiviral activities of SERINC5 and ADAM17." (PMID 40678214, 2025). "Serine incorporator 5 (SERINC5) suppressed HIV-1 infection at the entry step by affecting viral envelope glycoprotein-mediated virus-target cell fusion." (PMID 36591809, 2023). "SERINC5 is thought to inhibit HIV-1 infection by targeting the step of fusion between the viral lipid envelope and the host cell plasma membrane." (PMID 34001619, 2021). "Here, we show that SERINC5-mediated nef-defective HIV-1 infection inhibition is evolutionarily conserved." (PMID 33883219, 2021). "Recent studies have clearly demonstrated that Nef can downregulate host SERINC5, which ultimately promotes HIV-1 infection." (PMID 33329486, 2020). "Thus, CRL3KLHL20 plays a critical role in SERINC5 intracellular trafficking, antiviral activity, and expression during HIV-1 infection." (PMID 35474067, 2022). "Thus, further understanding the biology of K33/K48-linked chains will collect new insights into the general mechanism for integral cellular membrane expression and the arms race between SERINC5 and Nef during HIV-1 infection." (PMID 35474067, 2022). "Given that we demonstrated the role of c-Cbl in regulating HIV-1 Nef protein levels, we believe that c-Cbl-mediated downregulation of HIV-1 Nef could inhibit HIV-1 infection through facilitating SERINC5-mediated antiviral activity." (PMID 33329486, 2020). "Yet, SERINC5 has been shown to enhance MDA5-mediated IFN signaling, and SERINC5 can interact with MAVS and TRAF6 to inhibit HIV-1 infection." (PMID 36223419, 2022). "The results showed that mRNA levels of already known host restriction factors which inhibit HIV-1 infection, TRIM5α, MX2, SAMHD1, SERINC3, SERINC5, IFITM2, IFITM3, ApoE, and PSGL-1 were not significantly elevated by γ-IFN." (PMID 35883685, 2022). "Importantly, evasion from restriction was not due to complete exclusion of SERINC5 from ΔCT virus, consistent with the notion that SERINC5 incorporation may be necessary but is not sufficient for restriction of HIV-1 infection." (PMID 34001619, 2021).
viral infection (11 papers, 2019 to 2025). "Within a putative ExxxLL motif of S2, two leucine residues determine S2’s SERINC5-antagonising ability, mutation of two leucines leads to S2 losing the ability to promote viral infection in the presence of SERINC5." (PMID 39902183, 2024). "SERINC5 has been shown to translocate to the mitochondrial membrane after viral infection, where it associates with MAVS and promotes its oligomerization." (PMID 36876111, 2023). "Moreover, SERINC5 disrupts membrane asymmetry, which is closely associated with alterations in the structure of Env and a decrease in viral infection ability." (PMID 39902183, 2024). "For instance, the infection by the classical swine fever virus (CSFV), which causes a highly contagious viral disease in pigs, reduces SERINC5 expression by an unknown mechanism." (PMID 36876111, 2023). "This experimental approach, utilizing a specific SERINC5 antibody, facilitates the detection and quantification of SERINC5 levels post-infection, thereby elucidating the role of SERINC5 in viral infections." (PMID 39902183, 2024). "This review summarizes the interaction between SERINC5 and viral replication, providing a promising avenue for fighting viral diseases." (PMID 39902183, 2024). "Based on the key role of SERINC5 in virus infection, we have analyzed the expression of SERINC5 during SARS-CoV-2 infection in two distinct cell lines from a GEO dataset." (PMID 36876111, 2023). "Different viruses have developed strategies to antagonize SERINC5 function but, how SERINC5 is controlled during viral infection is poorly understood." (PMID 36876111, 2023). "Surprisingly, in both cell types the levels of MAVS protein increased when those of SERINC5 decreased during viral infection, suggesting the involvement of a SERINC5-independent and positive regulatory mechanism of MAVS." (PMID 36876111, 2023). "In contrast, in HIV-1, VSV, and ZIKV, SERINC5 inhibits virus infection by interacting with the outer mitochondrial membrane protein MAVS facilitating its aggregation and, consequently, triggering the activation of downstream signaling pathways." (PMID 36876111, 2023). "Recent findings showing that SERINC5 modulates viral infection as an innate immunity factor suggest that the role of SERINC5 is more complex than previously thought." (PMID 36656836, 2023). "The results showed that SERINC5 overexpression in the virus target cells reduced virus infection by 5-fold, and consistently, SERINC5-knockout increased WSN-Gluc infection." (PMID 36223419, 2022). "The host cell protein serine incorporator 5 (SERINC5) is a transmembrane protein with antiviral effect that inhibits both viral infection and virus fusion early in the viral replication cycle." (PMID 36205528, 2022). "Only SERINC3 and SERINC5 of SERINC family can inhibit viral infection through the prevention of viral fusion and act as restriction factors early in the viral life cycle." (PMID 33013817, 2020). "SERINC5 is a novel host restriction factor that defends against viral infections, including that of murine leukemia virus (MLV), human immune deficiency virus (HIV) and equine infectious anemia virus (EIAV)." (PMID 33013817, 2020). "Serine incorporator 5 (SERINC5), a multipass transmembrane protein, protects cells from viral infections." (PMID 33013817, 2020). "The regulation between host factors and SERINC5 after virus infection." (PMID 39902183, 2024). "This fact again supports the key role of SERINC5 in the host defense against viral infection." (PMID 36876111, 2023). "Future studies integrating the different aspects of SERINC5 during virus infection are needed." (PMID 36656836, 2023). "Therefore, a better understanding of the extent of the antiviral functions of SERINC5 is critical for the design of SERINC5-based therapeutic approaches aimed at treating virus infections." (PMID 37766367, 2023). "We also examined the kinetics of SERINC5 translocation during virus infection." (PMID 36223419, 2022).
viral infection (continued). "In viral infection cycles, many host membrane-associated antiviral factors could block their replication, such as bone marrow stromal antigen 2 (BST-2), serine incorporator 5 (SERINC5, SER5), membrane-associated RING-CH protein 8 (MARCH8), and interferon-induced transmembrane protein 3 (2, –, 5)." (PMID 39868869, 2025). "SERINC5 overexpression inhibits WNS HA/NA-mediated infection, whereas SERINC5 knockout increased virus infection." (PMID 36223419, 2022). "Despite the promising insights into SERINC5’s role in viral infections, there exists a conspicuous lack of research examining its potential impact on bacterial, parasitic, and fungal infections." (PMID 39902183, 2024). "It is reported that SERINC5 interacts with MAVS and enhances the formation of MAVS polymers at mitochondria after virus infection, which recruits TRAF6, are essential for NF-κB signaling (NF-κB is the transcription for IFN in response to viral infections and immune responses)." (PMID 39902183, 2024). "This is in agreement with the idea that exclusion of SERINC5 from virions is important but not adequate for alleviation of restriction of virus infection." (PMID 35618710, 2022). "However, it is noted that INF–α does not increase the SERINC5 mRNA level, which occurs in cells without viral infection." (PMID 39902183, 2024).
COVID-19 (2 papers, 2023 to 2024). A disease caused by infection with severe acute respiratory syndrome coronavirus 2. "observe a reduction in SERINC5 mRNA levels in COVID-19 patients, as well as a decrease in SERINC5 mRNA at 4 hours post-infection and a decline in SERINC5 protein levels at 16 hours post-infection in Vero E6 and HEK293T-hACE2 cells." (PMID 39902183, 2024). "Then, we evaluated the level of SERINC5 mRNA in nasopharyngeal (swabs) and saliva samples from patients with COVID-19 and controls." (PMID 36876111, 2023). "We found an anti-correlative expression between these two svRNAs and SERINC5 in different biological samples, including samples from COVID-19 patients." (PMID 36876111, 2023). "Here, we demonstrated that levels of SERINC5 were reduced during the infection by SARS-CoV-2 both in cell cultures and in COVID-19 patients." (PMID 36876111, 2023).
influenza (2 papers, 2022 to 2025). An acute viral infection of the respiratory tract, occurring in isolated cases, in epidemics, or in pandemics; it is caused by serologically different strains of viruses (influenzaviruses) designated A, B, and C, has a 3-day incubation period, and usually lasts for 3 to 10 days. "Analysis of the amino acid sequences of influenza HA1 strains indicates that HA glycosylation sites correlate with the sensitivity of influenza HA to SERINC5, and the inhibitory effect of SERINC5 was lost when certain HA glycosylation sites were mutated." (PMID 36223419, 2022). "Given the strong effect of perturbations to liquid-ordered membrane components on IAV fusion and prior work showing that host restriction factors such as IFITM3 and Serinc5 alter membrane order and stiffness, we hypothesized that similar effects may control influenza fusion with the plasma membrane." (PMID 40704989, 2025).
infection (25 papers, 2018 to 2026). The state of being infected such as from the introduction of a foreign agent such as serum, vaccine, antigenic substance or organism. "HIV-1 Nef and MLV glycoGag are unrelated viral proteins, yet both counteract the same host restriction factor, SERINC5, to facilitate productive infection." (PMID 40093084, 2025). "A single study using cell-free infection of MDMs with ∆Nef-viruses produced with SERINC5 showed that restriction was dependent of the monocyte donor." (PMID 40294108, 2025). "Toward this, macrophages were primed with VSV-G-enveloped vesicles carrying SERINC5 or conditioned media (detailed in the Materials and Methods section) 6 h prior to infection." (PMID 36976020, 2023). "A clear reduction in the levels of SERINC5 protein throughout the infection was detected, with their lowest values at 16 and 20 hpi in both cell lines." (PMID 36876111, 2023). "Altogether, these data indicated that the infection of SARS-CoV-2 induced a reduction in the levels of SERINC5 mRNA." (PMID 36876111, 2023). "We have also shown that Tat binding to MCE1 is lost only in the case when the infection is initiated with SERINC5 incorporated virus and upon upregulation of RPL35 and DRAP1." (PMID 36976020, 2023). "Infection from HIV-1 (SERINC5+) in macrophages upregulated RPL35 by ~5-fold and DRAP1 by ~3-fold at the RNA level, which was, importantly, reversed when the viruses were produced in the presence of viral accessary protein Nef." (PMID 36976020, 2023). "Differential gene expression analysis (detailed in the Materials and Methods section) revealed candidates that were positively regulated upon infection with HIV-1 (SERINC5+)." (PMID 36976020, 2023). "Even when SARS-CoV-2 is equipped to counteract SERINC5, we would expect a defect in replication since SERINC5 was already present in our cells prior to the infection and the subsequent synthesis of ORF7a and svRNAs—the SERINC5 antagonists in SARS-CoV-2." (PMID 37766367, 2023). "We measured the SERINC5 down-regulation activity of 106 subtype C Nef clones, isolated from individuals in early infection, for which the Nef activities of CD4 and HLA-I down-regulation as well as alteration of TCR signalling were previously measured." (PMID 37004071, 2023). "Regardless, the number of attached particles at time zero, as well as viral uptake at 2 h post-infection, is comparable between Parental and SERINC5-KO cells." (PMID 37766367, 2023). "Similar results were obtained when viruses incorporating endogenous SERINC5 were used for infection." (PMID 36976020, 2023). "The impact of SERINC5 on virus proteins was examined 16 h post-infection—which would correspond to one full cycle of replication." (PMID 37766367, 2023). "The in silico study revealed a decrease of SERINC5 mRNA during the infection course, suggesting that SARS-CoV-2 antagonizes SERINC5 activity by downregulating its expression." (PMID 36876111, 2023). "On the contrary, they progressively increased, suggesting that a SERINC5-independent mechanism would be responsible for the augmentation in MAVS during infection." (PMID 36876111, 2023). "Although the main reported viral mechanism to antagonize the antiviral activity of SERINC5 is to relocate SERINC5 within the cell, it has been shown that expression of SERINC5 can also be down-regulated upon the infection both in vitro and in vivo." (PMID 36876111, 2023). "The analysis of GSE148729 data showed that SERINC5 mRNA levels progressively decrease with the time of infection in Calu3 cells." (PMID 36876111, 2023). "To address this limitation, we examined this activity of SERINC5 in a more physiologically relevant system: using the endogenous levels of the protein and under conditions of infection." (PMID 37766367, 2023). "A reduction in both SERINC1 and SERINC5 was detected 24 h and 48 h post-infection, but this was likely due to the cytopathic effects or the shutoff activity of the virus, since the actin levels were also considerably decreased." (PMID 37766367, 2023).